MTHFD1 (methylenetetrahydrofolate dehydrogenase, cyclohydrolase and formyltetrahydrofolate synthetase 1)
Diseases named in the same sentence as MTHFD1 in open-access papers (continued):
Sharing a sentence is not in itself a finding about the gene and the disease.
cervical cancer (2 papers, 2021 to 2023). A primary or metastatic malignant neoplasm involving the cervix. "Besides that, low transcript levels retrieved from TCGA primary tumors for three of the 11 ‘hub proteins’ (ALDH7A1, GOT1, MTHFD1) were associated with poor overall survival in renal and cervical cancer (p-value ≤ 0.05; Human Protein Atlas platform)." (PMID 34186243, 2021).
leukopenia (2 papers, 2020 to 2025). "IMPDH2 and MTHFD1 are involved in nucleic acid metabolism and are responsible for perm reduction and leukopenia." (PMID 32362827, 2020).
lung adenocarcinoma (2 papers, 2024 to 2025). A carcinoma that arises from the lung and is characterized by the presence of malignant glandular epithelial cells. "A current study found that MTHFD1 levels were not only associated with prognosis after CRT treatment of small cell lung cancer patients, but could also discriminate SCLC from both lung squamous cell carcinoma (LUSC) and lung adenocarcinoma (LUAD)." (PMID 39857769, 2025).
neuroblastoma (2 papers, 2024 to 2025). Neuroblastoma (NB) is the most common solid, extracranial childhood tumor. "The published data confirmed that the knockdown of MTHFD1 inhibited the proliferation, migration, and induced apoptosis of neuroblastoma (NB) cells." (PMID 39857769, 2025).
ovarian carcinoma (2 papers, 2021 to 2023). A malignant neoplasm originating from the surface ovarian epithelium. "Certainly, further research is needed in order to better unravel the role of the MTHFD1 1958 A>G variant in ovarian cancer risk, as this protein may be a potential therapeutic target for future ovarian cancer therapies." (PMID 37628752, 2023). "We found an association of the MTHFD1 rs2236225 (R653Q) variant with ovarian cancer." (PMID 37628752, 2023). "Cancers of the female reproductive system are strongly associated with the occurrence of depression, and ovarian cancer may be associated with the rs2236225 variant of the MTHFD1 gene." (PMID 37628752, 2023). "Cancers of the female reproductive system are associated with the occurrence of depression, and ovarian cancer may be associated with the rs2236225 variant of the MTHFD1 gene." (PMID 37628752, 2023). "A relationship between the 401G>A, rs1950902 polymorphism of the MTHFD1 gene, and ovarian cancer was also not found in a meta-analysis of 16 independent studies including 5195 cases and 9276 controls." (PMID 37628752, 2023).
pancreatic carcinoma (2 papers, 2022 to 2025). "The activation of MTHFD1‐Kcr promotes the development of pancreatic cancer by increasing resistance to ferroptosis." (PMID 39477811, 2025). "A metabolic crisis in pancreatic carcinoma cells was described after DMF treatment through the down-regulation of methylenetetrahydrofolate dehydrogenase (MTHFD1) and methylenetetrahydrofolate dehydrogenase (NADP+ Dependent) 1 Like (MTHFD1L), two enzymes implicated in folate metabolism." (PMID 36552824, 2022).
prostate carcinoma (2 papers, 2018 to 2025). A carcinoma that arises from epithelial cells of the prostate gland. "Our study suggested a significant correlation between the upregulation of MTHFD1 and LGALS4 and an increased risk of prostate cancer." (PMID 39857769, 2025). "Our research has shown that MTHFD1 is widely expressed in malignant prostate cancer cells, mast cells, and macrophages." (PMID 39857769, 2025). "MME and MTHFD1 are a pair of proteins that interact in prostate cancer cells; however, the complex structure of these proteins has not been determined." (PMID 29745830, 2018). "Additionally, MTHFD1 may form a nuclear complex with the phosphatase and tensin homologue deleted on chromosome 10 (PENT) to assist dTMP synthesis in human prostate cancer cell lines that may have implications for targeting nuclear-excluded PTEN prostate cancer cells with antifolate drugs." (PMID 39857769, 2025).
spina bifida (2 papers, 2009 to 2025). A congenital neural tube defect in which vertebrae are not fully formed. "We did observe a modestly elevated spina bifida risk for individuals who were homozygous for another MTHFD1 SNP (rs2236224) and modestly lowered risks for three others (hcv11462908, rs702465, and rs7571842)." (PMID 19493349, 2009). "Genetic factors including variations in some specific genes such as MTHFR, MTHFD1, MTRR, VANGL1, VANGL2, CELSR1, and FUZ, as well as variants in the T-locus on chromosome 6q have also been studied in the development of spina bifida and other spinal dysmorphisms." (PMID 39835283, 2025).
ventricular septal defect (2 papers, 2021 to 2024). The presence of a defect (opening) in the septum that separates the two ventricles of the heart. "This study aimed at assessing the association between maternal methylenetetrahydrofolate dehydrogenase 1 (MTHFD1) gene polymorphisms, maternal dietary habits, and their interactions with the risk of ventricular septal defects (VSD) in offspring." (PMID 35186819, 2021). "Song and colleagues aimed at assessing the association between maternal methylenetetrahydrofolate dehydrogenase 1 (MTHFD1) gene polymorphisms, maternal dietary habits in early pregnancy, and their interactions with the risk of ventricular septal defects (VSD) in offspring." (PMID 38613027, 2024).
acute myeloid leukemia (1 paper, 2024). Acute myeloid leukemia (AML) is a group of neoplasms arising from precursor cells committed to the myeloid cell-line differentiation. "MTHFD1 can also promote tumorigenesis and lead to drug resistance by regulating NADPH homeostasis in the one-carbon metabolism process in acute myeloid leukemia." (PMID 38336749, 2024).
Alzheimer disease (1 paper, 2022). A progressive, neurodegenerative disease characterized by loss of function and death of nerve cells in several areas of the brain leading to loss of cognitive function such as memory and language. "We measured folate metabolites and enzymes in tissue lysates of normal and Alzheimer’s disease individuals with negative SNPs in MTHFD1 and/or MTHFR and compared these to normal and Alzheimer’s disease individuals with normal or neutral SNPs in these genes." (PMID 35736408, 2022).
chronic myelogenous leukemia (1 paper, 2024). "Inhibiting MTHFD1 in chronic myelogenous leukemia causes a significant decrease in the proliferative ability of tumor cells both in vitro and in vivo." (PMID 38336749, 2024).
dyslipidaemia (1 paper, 2022). "Furthermore, the MTHFD1 variant (rs1076991) minor T-allele has been associated with an approximately 62.5% drop-in transcription rate of the MTHFD1 enzyme, which could also be associated with intercellular SAM accumulation, conditions that lead to dyslipidaemia and the consequent increased CVD risk." (PMID 35987633, 2022).
endometrial cancer (1 paper, 2024). Primary or metastatic malignant neoplasm involving the endometrium (mucous membrane that lines the endometrial cavity). "This investigation revealed that the MTHFD1 mRNA levels were distinctly elevated in the bladder, colorectal, esophageal, head, and neck, lung, prostate, gastric, and endometrial cancers compared to the normal tissues." (PMID 39571599, 2024).
fatty liver (1 paper, 2025). "Low choline diet led to transcriptional changes in peripheral lymphocytes.Gene signature associated with the presence or absence of organ dysfunction (fatty liver and elevated plasma CRP).SNPs in MTHFD1, CHDH and PEMT influence the diet-induced changes in gene expression profile." (PMID 40821837, 2025).
Gestational Diabetes Mellitus (1 paper, 2024). "This study investigated the association between the MTHFD1 G1958A polymorphism, which is involved in folate metabolism, and gestational diabetes mellitus (GDM) risk." (PMID 38435941, 2024).
gynecologic cancers (1 paper, 2023). "MTHFD1 rs2236225 was associated with an increased risk of gynecologic cancers (in dominant OR = 1.53, p = 0.033, and in log-additive models OR = 1.37, p = 0.024)." (PMID 37628752, 2023). "Analysis of the dataset of gynecologic cancers and controls revealed synergistic interactions between MTHFD1 rs2236225 and MTHFR rs1801133 (IG = 0.06%) and MTHFR rs1801133 and MTR rs1805087 (IG = 0.08%)." (PMID 37628752, 2023).
ischemic stroke (1 paper, 2025). A stroke disorder caused by obstruction of blood flow to the brain, due to thrombotic (local blood clot formation) or embolic (due to a blood clot or other material traveling from another site) event. "Ischemic stroke affected levels of neuronal MTHFD1 levels in cortical brain tissue (F = 9.74, p = 0.0075)." (PMID 40950018, 2025).
metastatic cancer (1 paper, 2021). A carcinoma which has spread from the original site of growth to another anatomic site. "Notably, while the inhibition of both the cytosolic and mitochondrial SHMT isoforms was effective for both primary and metastatic cancer cell lines, targeting only cytosolic activities by inhibition of DHFR or MTHFD1, inhibited proliferation selectively in the metastatic cell lines." (PMID 33498690, 2021).
methylmalonic acidemia (1 paper, 2017). A genetically heterogenous inherited disorder characterized by abnormalities in the metabolism of lipids and proteins. "Possibly, additional biochemical abnormalities such as methylmalonic acidemia and/or methionine deficiency—as in cblC defect (this study) or in methylenetetrahydrofolate dehydrogenase 1 (MTHFD1) deficiency (OMIM 172460,)—are required to develop TMA." (PMID 27289364, 2017).
non-small cell lung carcinoma (1 paper, 2025). A group of at least three distinct histological types of lung cancer, including non-small cell squamous cell carcinoma, adenocarcinoma, and large cell carcinoma. "Furthermore, the expression level of MTHFD1 was associated with survival time, tumor size, TNM stage, histologic grade, and metastasis in non-small cell lung cancer and that MTHFD1 expression in tumor tissues and cells was significantly elevated compared to adjacent normal tissues and cells." (PMID 39857769, 2025).
Parkinson disease (1 paper, 2025). A progressive degenerative disorder of the central nervous system characterized by loss of dopamine producing neurons in the substantia nigra and the presence of Lewy bodies in the substantia nigra and locus coeruleus. "The observed deficiencies of MTHFR, MTHFD1, DHFR, SPR and PTPS suggest a direct and critical impact on the choroid plexus in Parkinson’s disease (PD)." (PMID 40422884, 2025).
rectal cancer (1 paper, 2017). A primary or metastatic malignant neoplasm that affects the rectum. "Therefore, the gene expression levels of four genes, HIF1A, MTHFD1, GGH and TYMS, in tumor tissues before CRT may be useful for predicting the efficacy of preoperative CRT including S-1 or UFT/LV in patients with rectal cancer." (PMID 28417167, 2017).
squamous cell carcinoma (1 paper, 2024). A carcinoma arising from squamous epithelial cells. "In the TCGA datasets of the two main subtypes of NSCLC, adenocarcinoma (LUAD) and squamous cell carcinoma (LUSC), PSAT1, SHMT1, SHMT2, MTHFD1 and MTHFD2 were significantly overexpressed compared to normal lung tissue." (PMID 38515202, 2024).
Stroke (1 paper, 2025). Sudden impairment of blood flow to a part of the brain due to occlusion or rupture of an artery to the brain. "Both female and male stroke patients showed significantly elevated levels of MTHFD1, SHMT, and TS compared to healthy controls." (PMID 40950018, 2025). "The importance of 1C metabolism can also be seen by the increases in MTHFD1, SHMT, TS, and CBS in both stroke females and males in the present study." (PMID 40950018, 2025).
thromboembolic disease (1 paper, 2025). "One study analyzed a family with hereditary HHC, and its findings showed that the proband with severe thromboembolic disease who failed to accept folic acid therapy carried a homozygous variant of the MTHFD1 gene, which did not occur in the sons who were sensitive to folic acid therapy." (PMID 40647238, 2025).
type 2 diabetes (1 paper, 2012). "On the other hand, in OW/OB individuals, MTHFD1-rs1076991 (OR = 0.81 (95% CI 0.69–0.95) P = 0.01) and TCN2-rs1801198 (OR = 0.85 (95% CI 0.72–0.99), P = 0.04) showed nominal association with type 2 diabetes." (PMID 21960995, 2012).
cancer (42 papers, 2013 to 2025). A tumor composed of atypical neoplastic, often pleomorphic cells that invade other tissues. "Together, this indicates that TH9619 causes thymidylate deficiency in MTHFD2-expressing cancer cells by inhibiting MTHFD1(DC), leading to 10-CHO-THF trapping and depletion of THF." (PMID 37012496, 2023). "Only for MTHFD1 in the rs2236225 locus did we observe higher frequency of the A allele in women with cancers—0.420% vs. 0.346% in controls (OR: 1.369; 95% CI: 1.04–1.80; p = 0.023, pcorr = 0.071)." (PMID 37628752, 2023). "TH9619 inhibition of MTHFD1(DC) causes accumulation of the 1C intermediate 10-CHO-THF in MTHFD2-expressing cancer cells (a mechanism we term ‘folate trapping’)." (PMID 37012496, 2023). "Allele A MTHFD1 rs2236225 was more common in cancer patients than in controls (42.0% vs. 34.6%, OR = 0.730, 95% CI: 0.55–0.96, p = 0.024)." (PMID 37628752, 2023). "We found that inhibition of the DC domain of MTHFD1 by TH9619 causes thymineless death specifically in MTHFD2-expressing cancer cells." (PMID 37012496, 2023). "This study demonstrates that the MTHFD1 1958GG genotype shows a higher frequency among cancer patients and it is associated, in all the study subjects, to PBMCs DNA hypomethylation as compared to the A allele carriers." (PMID 28968444, 2017). "When global DNA methylation was analysed according to MTHFD1 1958G>A genotypes, the 1958GG genotype was either significantly more represented in patients affected by cancer, and associated with lower mCyt levels in PBMCs DNA." (PMID 28968444, 2017). "In recent years, many studies have been conducted to investigate the association between MTHFD1 polymorphisms and cancer risk in humans across different countries." (PMID 23894459, 2013). "A variety of molecular epidemiological studies have focused on the associations between MTHFD1 polymorphisms and cancer susceptibility." (PMID 23894459, 2013). "With respect to other cancers, the results indicated that MTHFD1 G1958A was significantly associated with a decreased other cancers risk under recessive model." (PMID 23894459, 2013). "Then in order to obtain the exact consequence of the relationship between MTHFD1 polymorphisms and cancer susceptibility, stratified analyses by ethnicity and cancer type were performed." (PMID 23894459, 2013). "A comprehensive search was conducted to determine all the eligible studies about MTHFD1 polymorphisms and cancer risk." (PMID 23894459, 2013). "Combined odds ratios (ORs) and 95% confidence intervals (CIs) were used to assess the strength of the association between the MTHFD1 polymorphisms and cancer risk." (PMID 23894459, 2013). "The MTHFD1 rs2236225 AA genotype was associated with an increased risk of cancers (GG vs. AA, OR = 1.83, 95%: 1.02–3.28, p = 0.073; in dominant model GG vs. GA-AA, OR 1.53, 95%: 1.03–2.25, p = 0.033, AIC = 605.8; and in log-additive model OR = 1.37, 95%: 1.04–1.81, p = 0.024, AIC = 605.2)." (PMID 37628752, 2023). "In addition, MTHFD1 also plays an important role in the stemness of cancer cells, while cancer stem cells are also highly associated with chemoresistance." (PMID 33934113, 2021). "The MTHFD1 1958AA genotype is linked to a significantly reduced cancer risk." (PMID 28968444, 2017). "Further studies are certainly needed to better unravel the role of MTHFD1 1958 A>G in cancer risk." (PMID 28968444, 2017). "During the extraction of data, 17 articles were excluded, because they did not provide sufficient data needed for OR calculation, evaluating other polymorphisms of MTHFD1 and cancers, were review articles or their contents associated with cancer prognosis and therapy, leaving 22 articles." (PMID 23894459, 2013). "Moreover, further evaluating the effect of gene–gene and gene–environment interactions on the MTHFD1 polymorphisms and cancer risk are necessary." (PMID 23894459, 2013). "This suggests the multifaceted role of MTHFD1 in cancer cell metabolism and the tumor microenvironment." (PMID 39857769, 2025).